TRIM8 (tripartite motif containing 8)
Description:
E3 ubiquitin-protein ligase that participates in multiple biological processes including cell survival, differentiation, apoptosis, and in particular, the innate immune response. Participates in the activation of interferon-gamma signaling by promoting proteasomal degradation of the repressor SOCS1. Plays a positive role in the TNFalpha and IL-1beta signaling pathways. Mechanistically, induces the 'Lys-63'-linked polyubiquitination of MAP3K7/TAK1 component leading to the activation of NF-kappa-B. Also modulates STAT3 activity through negative regulation of PIAS3, either by degradation of PIAS3 through the ubiquitin-proteasome pathway or exclusion of PIAS3 from the nucleus. Negatively regulates TLR3/4-mediated innate immune response by catalyzing 'Lys-6'- and 'Lys-33'-linked polyubiquitination of TICAM1 and thereby disrupting the TICAM1-TBK1 interaction.
Synonyms: GERP; RNF27; FSGSNEDS
Tractability: PROTAC: ubiquitination databases record sites on it.
Gene: Protein-coding gene on chromosome 10 (102,642,503 to 102,662,789, forward strand). Ensembl gene ENSG00000171206.
Subcellular location: Cytoplasm; Nucleus; Nucleus, nuclear body
Subcellular location (Human Protein Atlas): Nucleoplasm; Cytosol; Vesicles
Pathways (Reactome):
Immune System: Interferon gamma signaling
Gene Ontology:
Molecular function: identical protein binding; protein binding; protein homodimerization activity; transcription coactivator activity; ubiquitin protein ligase activity; zinc ion binding
Biological process: antiviral innate immune response; canonical NF-kappaB signal transduction; positive regulation of autophagy; positive regulation of canonical NF-kappaB signal transduction; protein K63-linked ubiquitination; suppression of viral release by host; host-mediated suppression of symbiont invasion; innate immune response; positive regulation of DNA-templated transcription; protein ubiquitination
Cellular component: cytoplasm; cytosol; nucleoplasm; nucleus; PML body; nuclear body
Genetic constraint (gnomAD): Loss-of-function variants: 9 observed, 54.04 expected, observed/expected ratio (o/e) 0.17, 90% interval 0.099 to 0.29. The upper end of that interval is the gene's LOEUF score, 0.29, which puts it in group 1 of 6, group 1 being the genes least tolerant of losing a copy. Missense variants: 556 observed, 743.46 expected, observed/expected ratio (o/e) 0.75, 90% interval 0.7 to 0.8. Synonymous variants: 335 observed, 338.33 expected, observed/expected ratio (o/e) 0.99, 90% interval 0.9 to 1.08.
Gene-disease validity (ClinGen):
ClinGen rates the evidence that TRIM8 causes each of these diseases.
focal segmental glomerulosclerosis and neurodevelopmental syndrome (autosomal dominant): Definitive. A Mendelian diseases characterized by global developmental delay and renal dysfunction manifest as proteinuria and nephrotic syndrome apparent from infancy or early childhood.
Homologues: Orthologues: chimpanzee TRIM8 (99% identical), macaque TRIM8 (99% identical), pig TRIM8 (99% identical), rat Trim8 (98% identical), mouse Trim8 (98% identical), tropical clawed frog trim8 (84% identical), rabbit TRIM8 (75% identical), zebrafish trim8b (69% identical), guinea pig TRIM8 (69% identical), zebrafish trim8a (68% identical), dog TRIM8 (65% identical). Paralogues in human: TRIM46 (18% identical), TRIM62 (17% identical), TRIM36 (16% identical), TRIM24 (16% identical), TRIM33 (16% identical), TRIM9 (16% identical), TRIM67 (15% identical), TRIM2 (15% identical), TRIM71 (15% identical), TRIM3 (15% identical), TRIM37 (15% identical), TRIM28 (14% identical), and 68 more.
Diseases named in the same sentence as TRIM8 in open-access papers:
TRIM8 is named in the same sentence as 90 diseases in open-access papers, as found by Europe PMC text mining. Sharing a sentence is not in itself a finding about the gene and the disease. The quoted sentences say what the papers report.
glioblastoma (12 papers, 2015 to 2024). The most malignant astrocytic tumor (WHO grade IV). "They observed that patients affected by glioblastomas were characterized by a frequent deletion or loss of heterozygosity in the TRIM8 gene, which causes the loss of gene copy number associated with the inactivation of TRIM8 in glioblastoma cells." (PMID 35565438, 2022). "For the first time, the link between TRIM8 and cancer was observed in glioblastoma, where it was observed that the TRIM8 genomic locus was subject to frequent deletion or loss of heterozygosity." (PMID 33807506, 2021). "Involvement of TRIM8 in cancer was first highlighted in brain tumours including glioblastomas, where the TRIM8 loss of heterozygosity was observed." (PMID 29182544, 2017). "Our experimental data suggested that the inactivation of TRIM8 in glioblastoma cells may occurs primarily through the loss of gene copy number." (PMID 26077989, 2015). "TRIM8 acts as an oncogene in glioblastoma and Ewing sarcoma, but suppresses tumor growth in breast cancer and colorectal cancer." (PMID 38879600, 2024). "Recent research has shown that TRIM8 is a molecule of duality (MoD) that can function as both an oncogene and a tumor suppressor gene, making it a "double-edged sword" in glioblastoma development." (PMID 36690946, 2023). "TRIM8 is a part of a huge of proteins known as Tripartite Motif proteins, in the first instance described as a glioblastoma expressed RING-finger protein (GERP)." (PMID 35565438, 2022). "TRIM8, originally found in glioblastoma, is also a designated glioblastoma expressed RING finger protein (GERP), which is widely distributed and expressed in human tissues and tumors." (PMID 36353542, 2022). "TRIM8 gene (Ensembl: ENSG00000171206) is situated on chromosome 10q24.32, a region that is known to show frequent deletion or loss of heterozygosity in glioblastomas." (PMID 35565438, 2022). "TRIM8 regulates stemness in glioblastoma by activating STAT3 signaling and inhibiting the expression of PIAS3." (PMID 33923045, 2021). "TRIM8 gene maps on chromosome 10q24.3, within a region mostly involved in deletion or rearrangements in glioblastomas." (PMID 29182544, 2017). "TRIM8 (also known as ‘glioblastoma‐expressed ring finger protein’) is expressed equally in GBM and normal brain tissues, despite its hemizygous deletion in the large majority of GBMs, and its expression is highly correlated with stem cell markers." (PMID 28100038, 2017). "Specifically, the loss of one copy of TRIM8 gene was observed in approximately 9.9 % of gliomas of grade II, 32.8 % of grade III, and 91.8 % of glioblastomas (p < 0.001)." (PMID 26077989, 2015). "Moreover, it was shown both U87MG glioblastoma and patients’ primary glioma cell lines were characterized by the overexpression of TRIM8, which suppresses cell development and induces an important decrease in clonogenicity." (PMID 35565438, 2022). "In fact, TRIM8 was initially designated as a Glioblastoma-Expressed RING finger Protein (GERP)." (PMID 33807506, 2021). "Interestingly, hemizygous TRIM8 deletion does not lead to diminished expression, but rather is thought to promote gliomagenesis, leading to the gene product's alternative name, glioblastoma‐expressed RING finger protein (GERP)." (PMID 28100038, 2017). "Moreover, TRIM8 downregulation was also found in other tumours as Glioblastoma Multiforme (GBM), clear cell Renal Cell Carcinoma (ccRCC), anaplastic thyroid cancer (ATC), colorectal cancer (CRC), Chronic lymphocytic leukemia (CLL), and osteosarcoma cell lines." (PMID 29182544, 2017). "TRIM8 re-localizes from the cytoplasm of healthy neurons to the nucleus in GBM cells to establish a stem-like phenotype, with an increase in malignancy and glioblastoma stem cell markers, such as STAT3, SOX2, Nestin, and Nanog." (PMID 38115822, 2023). "Overexpression of TRIM8 leads to the higher expression of p-STAT3, c-MYC, SOX2, NESTIN, and CD133, and enhances self-renewal of glioblastoma stem cells." (PMID 33923045, 2021).
glioblastoma (continued). "We found that a restored TRIM8 expression induced a significant reduction of clonogenic potential in U87MG and patient’s glioblastoma cells." (PMID 26077989, 2015). "Specifically, a heterozygous deletion of TRIM8 was observed in approximately 11.1 % of gliomas of WHO grades I and II, 30.8 % of grade III, and 47.8 % of glioblastomas." (PMID 26077989, 2015). "It has been reported that TRIM8 cancels the negative effect of PIAS3 on STAT3 by degradation of PIAS3 and enhances Src-dependent tumorigenesis of glioblastoma." (PMID 38879600, 2024).
glioma (11 papers, 2015 to 2023). A benign or malignant brain and spinal cord tumor that arises from glial cells (astrocytes, oligodendrocytes, ependymal cells). "TRIM8 maps to chromosome 10q24.3, a region showing frequent deletion and loss of heterozygosity in human glioma." (PMID 26077989, 2015). "As in breast cancer, and also in other cancers, low expression levels of TRIM8 are associated with a poor prognosis for the patients; in fact, TRIM8 is downregulated in Glioma, Chronic lymphocytic leukemia (CLL), Renal Clear Cell Carcinoma (ccRCC), CRC and in melanoma." (PMID 33673719, 2021). "To investigate the mechanisms that may cause the reduction of TRIM8 expression in glioma we sequenced the coding and untranslated regions of TRIM8 in 70 patients detecting any likely pathogenic variant (data not shown)." (PMID 26077989, 2015). "Indeed, deficiency in TRIM8 E3 ligase function in glioma cells might stimulate cancer development by promoting the oncogenes stabilization and/or increasing tumor suppressors degradation." (PMID 35565438, 2022). "TRIM8, a member of the TRIM superfamily, is abnormally expressed in high-grade gliomas and is associated with poor clinical prognosis in patients with glioma." (PMID 36690946, 2023). "TRIM8 downregulation in glioma is involved in cell proliferation, and it is related to patients’ survival." (PMID 35565438, 2022). "The effect of TRIM8 on patient glioma cell proliferation was evaluated by performing MTT and clonogenic assays." (PMID 26077989, 2015). "We detected a somatic heterozygous deletion encompassing the full TRIM8 gene in 27 out of 68 (39.7 %) analyzed glioma cells." (PMID 26077989, 2015). "TRIM8 RNA expression level was determined from 71 primary glioma cell lines: 8 (WHO grade I and II), 12 (III), 51 (IV) and 70 tumor tissues: 16 (WHO grade I and II), 10 (III), 44 (IV)." (PMID 26077989, 2015). "Our preliminary results suggest the existence of a feedback circuit involving miR-17 and TRIM8 for glioma pathogenesis." (PMID 26077989, 2015). "TRIM8 relative expression ranged from 0.09 to 1.65 in glioma cell lines and 0.01-16.13 in tumor tissues, respectively." (PMID 26077989, 2015). "Up regulation of miR-17, associated with advanced tumor progression and poor overall survival of gliomas, has been shown to reduce the levels of TRIM8 in primary chronic lymphocytic leukemia cells, although a direct regulation was not yet demonstrated." (PMID 26077989, 2015). "We found that a restored TRIM8 expression in patient glioma cell lines suppresses the tumor growth and induced a significant reduction of clonogenic potential." (PMID 26077989, 2015). "In this study, we showed that TRIM8 is down regulated in glioma tissues and cell lines and its expression inversely correlates with tumor grade." (PMID 26077989, 2015). "To confirm this evidence, we used the available TRIM8 copy number information from the 526 of TCGA cohort, detecting a heterozygous deletion of TRIM8 gene in 303 out of 526 (57.6 %) analyzed glioma tissues." (PMID 26077989, 2015). "We evaluated the association between TRIM8 expression and Overall Survival and Progression-free Survival in 180 grade II, 191 grade III and 564 grade IV gliomas of TCGA cohort." (PMID 26077989, 2015). "TRIM8 transcriptional level was profiled in our own glioma cases collection by qPCR and confirmed in the independent TCGA glioma cohort." (PMID 26077989, 2015). "Moreover, restored TRIM8 expression in patients glioma cell lines suppresses the tumor growth and induces a significant reduction of the clonogenic potential." (PMID 31137886, 2019). "In glioma tissues and cell lines, TRIM8 expression inversely correlates with tumor grade." (PMID 31137886, 2019). "In addition, we compared triplet signatures with previously identified prognosis-associated biomarkers in glioma, such as VSIG4 and TRIM8." (PMID 26943771, 2016). "39.3 %, and 28.9 %, respectively, in glioma TRIM8 expressing cells." (PMID 26077989, 2015).
glioma (continued). "Our study provides evidences that TRIM8 may participate in the carcinogenesis and progression of glioma and that the transcriptional repression of TRIM8 might have potential value for predicting poor prognosis in glioma patients." (PMID 26077989, 2015). "U87MG glioma cells, transfected with expressing TRIM8 or control vector (with transfection efficiency >80 %, measured by immunofluorescence, data not shown), were plated at limiting dilution and the formation of large colonies (>50 cells) was assessed after 3 weeks." (PMID 26077989, 2015). "Based on this group of experimental data, we can hypothesize that defects in TRIM8 E3 ligase activity in glioma cells might promote carcinogenesis and cancerous growth by contributing to oncogenes stabilization and/or enhancing tumour suppressors degradation." (PMID 26077989, 2015). "Overall these data suggested that TRIM8 expression levels might represent an independent predictor of survival in WHO grade III gliomas." (PMID 26077989, 2015). "Our data give preliminary evidences that TRIM8 may participate in the carcinogenesis and progression of glioma and that the transcriptional repression of TRIM8 might have potential value for predicting poor prognosis in glioma patients." (PMID 26077989, 2015). "We therefore investigated whether overexpression of TRIM8 affects clonogenic potential of glioma cells as an indirect index of their tumorigenic potential." (PMID 26077989, 2015). "Our study is the first that investigates the role of the E3 ubiquitin ligase TRIM8 in glioma." (PMID 26077989, 2015). "We showed that TRIM8 expression correlates with unfavorable clinical outcome in glioma patients." (PMID 26077989, 2015). "It has been demonstrated that miR-17-5p and miR-106b-5p directly target the 3′UTR of TRIM8 and both transcriptionally and post-transcriptionally repress the expression of TRIM8, indicating that TRIM8 and miR-17-5p/miR-106b-5p may be part of the same circuit involved in ccRCC and glioma pathogenesis." (PMID 29182544, 2017). "Additionally, in human gliomas, a heterogeneous group of primary malignant brain tumours with strong resistance to chemotherapy and radiotherapy, the reduction of TRIM8 expression, correlates with high levels of miRNA-17-5p, leading to an unfavourable clinical outcome of the patients." (PMID 29182544, 2017). "Moreover, our preliminary results suggest that TRIM8 and miR-17 may be part of a same circuit involved in glioma pathogenesis, although further experiments are needed to confirm the involvement of this modulation in gliomagenesis." (PMID 26077989, 2015). "For instance, the overexpression of miR-17-5p demonstrated in patients affected by ccRCC, CRC, Glioma and CLL results in TRIM8 downregulation that affects cell proliferation and is related to patients’ survival." (PMID 35565438, 2022). "TRIM8 is downregulated in a number of tumors, including clear cells renal cell carcinoma (ccRCC), anaplastic thyroid carcinoma (ATC), and glioma (GM)." (PMID 31137886, 2019). "In tumor tissue glioma, median TRIM8 relative expressions were 0.49 in GBM (IQR: 0.30-0.82), 0.81 in WHO grade III (IQR: 0.37-2.32) and 2.61 in WHO grade I-II (IQR:1.52-6.14) glioma." (PMID 26077989, 2015). "To evaluate the effect of TRIM8 in glioma cell proliferation, we transfected U87MG glioma cells with a vector expressing TRIM8 and measured cell viability by MTT assay at 24, 48 and 72 h post transfection, respectively." (PMID 26077989, 2015). "Moreover, the unfavorable clinical outcome of patients affected by glioma has been correlated with TRIM8 downregulation, and restoration of TRIM8 expression reduced the clonogenic potential of the U87MG glioma cell line." (PMID 33807506, 2021). "We next examined the transcriptional profile of TRIM8 in an independent cohort, i.e. the TCGA cohort, detecting a significant lower expression of TRIM8 in grade III glioma (Median:0.65, IQR:0.32-1.23) as compared with grade II glioma (Median: 1.05, IQR 0.63-1.79)." (PMID 26077989, 2015).
glioma (continued). "In order to assess whether miR-17 also regulates protein level of TRIM8 in glioma cells, we co-transfected U87MG cells with a pcDNA3-FLAG vector containing the ORF and 3′UTR of TRIM8 (hereafter named TRIM8-3′UTR), along with synthesized miR-17 or miR-17 inhibitor, respectively." (PMID 26077989, 2015).